RBP4 (retinol binding protein 4)
Diseases named in the same sentence as RBP4 in open-access papers (continued):
Sharing a sentence is not in itself a finding about the gene and the disease.
colorectal cancer (7 papers, 2017 to 2025). A primary or metastatic malignant neoplasm that affects the colon or rectum. "Our Kaplan–Meier survival analysis in the TCGA cohort revealed a trend suggesting an association between RBP4 expression levels and overall survival in patients with colorectal cancer (CRC)." (PMID 41007818, 2025). "Our study demonstrated that high RBP4 expression in colorectal cancer (CRC) tissues was significantly associated with pT status, lymph node metastasis, and advanced clinical stage according to the TNM classification." (PMID 41007818, 2025). "We further investigated whether RBP4 expression was associated with aggressive presentations of colorectal cancer using classifications based on low or stable microsatellite instability and constitutively active KRAS mutations." (PMID 28689994, 2017). "In this study, we aimed to investigate the expression patterns and potential clinical significance of IL-6 and RBP4 in colorectal cancer." (PMID 41007818, 2025). "This study provides comprehensive insights into the role of IL-6 and RBP4 in colorectal cancer (CRC)." (PMID 41007818, 2025). "For example, genomic studies revealed that liver metastases from the colon adenocarcinomas showed significantly higher RBP4 transcript than that in paired primary colorectal carcinomas." (PMID 36632438, 2022). "Notably, during the evaluation of RBP4 in colorectal cancer patients, positively stained macrophages were also observed within the tumor microenvironment." (PMID 41007818, 2025). "Furthermore, in colorectal cancer with amplified RBP4+NTS+ cancer cell subpopulations, macrophage-induced ADCP is more pronounced and correlates with a favorable prognosis." (PMID 38774870, 2024). "Indeed, our data show that STRA6 and RBP4 are upregulated in colorectal cancers compared with normal colon, and also in more advanced disease with worse prognosis." (PMID 28689994, 2017). "RBP4 expression was significantly elevated in colorectal cancer (CRC) tissues compared to adjacent non-tumorous tissues (p < 0.0001)." (PMID 41007818, 2025). "Furthermore, RBP4 and THBS2 have been reported to serve as biomarkers for the diagnosis of colorectal cancer." (PMID 31612481, 2020). "For CDIPT, there are essentially no published data on colorectal cancer; its positive correlation with RBP4 in our set, therefore, represents a novel observation that may reflect shared lipid/inositol metabolism but remains to be experimentally validated." (PMID 41007818, 2025). "According to these data above, we have a preliminary conclusion that serum RBP4 concentrations could be a valuable prognostic factor in colorectal cancer, while THBS2 could not." (PMID 29190912, 2017). "The potential role of serum RBP4 and THBS2 as biomarker in colorectal cancer (CRC) diagnosis has never been studied." (PMID 29190912, 2017).
hyperlipidemia (7 papers, 2013 to 2023). "In a cross-sectional study, patients with chronic HCV infection had lower RBP4 levels than did control subjects, and higher RBP4 levels were linked to lower ALT levels, hyperlipidemia, and high HOMA-IR scores." (PMID 33167521, 2020). "In addition, a predictive model was established using the combination of serum RBP4 and hyperlipidemia, showing some ability to estimate cognitive decline over a 3-year period (AUC = 0.671)." (PMID 37808505, 2023).
Sepsis (7 papers, 2009 to 2019). Sepsis is defined as life-threatening organ dysfunction caused by a dysregulated host response to infection. "The concomitant reduction in muscular glucose uptake and increase in hepatic glucose output could possibly favor an adequate stress response in the initial phase of critical illness and sepsis, which would explain the positive association between relatively high RBP4 and recovery from acute illness." (PMID 20932285, 2010). "In a more recent study, the RBP4 serum level was significantly reduced in critically ill patients independently of sepsis (as compared with the healthy control group), and their RBP4 level was closely correlated with liver function." (PMID 22568928, 2012). "Further studies in appropriate animal models of experimental sepsis are needed to clarify the potential pathogenetic role and metabolic consequences of RBP4 in critical illness." (PMID 20932285, 2010). "To investigate the regulation of RBP4 in patients with different etiologies of sepsis and septic shock, we performed extensive subgroup analyses." (PMID 20932285, 2010). "Low levels of circulating RBP4 and leptin were previously observed after burn injury or trauma or both, and low levels of adiponectin were reported in rats with sepsis." (PMID 19589139, 2009). "The impact of sepsis on the RBP4 levels of critically ill patients may be different in various underlying diseases." (PMID 28588245, 2017). "This raises the possibility that RBP4 could be an important component of the so-called anti-acute phase proteins, at least in patients with sepsis." (PMID 20932285, 2010). "Acute phase proteins were inversely correlated with RBP4 in sepsis patients." (PMID 20932285, 2010). "A recent study reported reduced RBP4 serum levels in patients with sepsis of pulmonary origin." (PMID 20932285, 2010). "Finally, acute phase proteins were inversely correlated with RBP4 in sepsis patients." (PMID 22568928, 2012). "Serum RBP4 was significantly reduced in ICU patients, independently of sepsis, as compared to healthy controls (P < 0.001)." (PMID 20932285, 2010). "In contrast, another ICU cohort study demonstrated that sepsis had a negligible impact on RBP4 levels in critically ill patients, regardless of the origin of illness." (PMID 28588245, 2017). "For the subgroups, RBP4 serum levels were lower in patients with sepsis than in those without sepsis." (PMID 24099047, 2013). "We found that AECOPD patients with sepsis had significantly lower RBP4 levels compared with patients without sepsis (mg/L; 47.4 [21.9–82.4] vs 83.1 [23.3–128.6], p = 0.008)." (PMID 24099047, 2013). "Our study shows that reduced serum concentrations of RBP4 are a general response in critically ill patients, independent of the origin of the critical illness (sepsis or nonsepsis)." (PMID 20932285, 2010). "Recently, low levels of serum RBP4 have been reported in critical ill patients with sepsis of pulmonary origin compared to nonseptic patients." (PMID 20932285, 2010). "Critically ill patients with sepsis on ICU admission had even lower circulating admission levels of RBP4 and leptin than did patients without sepsis." (PMID 19589139, 2009). "The surviving ICU patients had lower baseline international normalized ratios (INRs) of prothrombin time, model for end-stage liver disease (MELD) scores and sepsis rates, but higher estimated glomerular filtration rates (eGFRs) and RBP4 levels than non-surviving patients." (PMID 28588245, 2017). "Patients with sepsis had lower levels of RBP-4 than did nonseptic patients." (PMID 22272381, 2012). "As inflammatory disorders could considerably impact serum RBP4 concentrations, we next compared patients with sepsis (n = 85) with patients without sepsis (n = 38)." (PMID 20932285, 2010). "Patients with sepsis had lower levels of leptin and RBP4 than did nonseptic patients." (PMID 19589139, 2009).
Sepsis (continued). "We observed low circulating levels of adiponectin, RBP4, and leptin in critically ill patients on admission to the ICU, with lowest values in patients with sepsis, but also in patients not critically ill under acute surgical stress." (PMID 19589139, 2009). "In a different study, RBP4 levels were also lower in ICU patients, regardless of whether or not sepsis was present, compared with controls." (PMID 31569348, 2019). "We demonstrate that serum RBP4 levels were significantly reduced in ICU patients as compared to controls, independent of etiology of critical illness or origin of sepsis (pulmonary versus nonpulmonary), and they were closely related to liver and kidney function." (PMID 20932285, 2010).
acute myocardial infarction (6 papers, 2014 to 2025). Necrosis of the myocardium, as a result of interruption of the blood supply to the area. "Some studies report reduced serum RBP4 levels in acute myocardial infarction and in men with familial hypercholesterolemia, where lower RBP4 predicted ischemic events within two years, suggesting a role in AMI." (PMID 41303567, 2025). "We investigated the relationship between RBP4 levels and the presence and severity of angiographically proven CAD and determined its possible role in acute myocardial infarction (AMI)." (PMID 25142320, 2014). "In this study, we sought to investigate the relationship between RBP4 levels and the presence and severity of angiographically proven CAD, and to determine its possible role in acute myocardial infarction (AMI)." (PMID 25142320, 2014). "High RBP-4 increases blood pressure, and absence of RBP-4 decreases blood pressure, meaning that accelerated RBP-4 levels are correlated with the prevalence of hypertonia and myocardial infarction." (PMID 36902521, 2023).
Alzheimer disease (6 papers, 2016 to 2025). A progressive, neurodegenerative disease characterized by loss of function and death of nerve cells in several areas of the brain leading to loss of cognitive function such as memory and language. "In the animal experiment, VA metabolism was disrupted in Alzheimer’s disease (AD) model mice, indicated by increased hepatic VA level and reduced retinol binding protein 4 (RBP4) level." (PMID 40341393, 2025). "Regarding the involvement of RBP4 in cognitive disorders, a biochemical analysis indicated that RBP4 is a potential biomarker involved in immunological and coagulation pathways in Alzheimer’s disease." (PMID 37808505, 2023). "Elevated rpS6 phosphorylation along with increased brain RBP4 levels were previously found in Alzheimer’s disease mice on a HFD." (PMID 27138913, 2016). "In addition, our data revealed the effects of RBP4 of DEGs that are important to pathways in GCs, including oxidative phosphorylation, NAFLD, Alzheimer’s disease, fatty acid biosynthesis, AMPK signaling pathway, and insulin signaling pathway." (PMID 31412686, 2019).
carotid atherosclerosis (6 papers, 2014 to 2023). A thickening and loss of elasticity of the walls of carotid arteries that occur with formation of atherosclerotic plaques. "We examined the independent relationships of RBP4 concentrations with cardiometabolic risk, endothelial activation and carotid atherosclerosis." (PMID 24651174, 2014). "Recent studies have reported that circulating RBP4 levels were increased in individuals with established carotid atherosclerosis and were related to the severity of stenosis." (PMID 38129891, 2023). "This study aimed to investigate the changes in serum levels of retinol-binding protein 4 (RBP4) with cerebral infarction, relationship of RBP4 with oxidative stress and carotid atherosclerosis, and its possible role in cerebral infarction." (PMID 36304097, 2022). "Although there is a growing number of studies demonstrating the relationship of RBP4 with either coronary or carotid atherosclerosis to our knowledge, no previous studies have focused on patients with PAD." (PMID 34758835, 2021).
ischemic stroke (6 papers, 2018 to 2023). A stroke disorder caused by obstruction of blood flow to the brain, due to thrombotic (local blood clot formation) or embolic (due to a blood clot or other material traveling from another site) event. "In ischemic stroke patients, RBP4 > 48.75 lg/mL and GFAP < 0.07 ng/mL were found to be independent predictors of stroke subtypes after a multivariate logistic regression analysis." (PMID 37892701, 2023). "It was observed that ischemic stroke patients exhibited elevated levels of RBP-4, NT-proBNP, and endostatin, while they had lower levels of GFAP than ICH patients." (PMID 37892701, 2023). "Retinol-binding protein 4 (RBP-4) is a promising biomarker for distinguishing ischemic stroke from ICH." (PMID 37892701, 2023). "Thus, RBP4 might potentially be used as a diagnostic biomarker of ischemic stroke." (PMID 35082965, 2022). "Furthermore, the absence of a standard and stable measurement method to assess blood RBP4 levels restrict the potential clinical use of this marker in the follow-up of ischemic stroke." (PMID 30038059, 2018). "In a study of 189 patients (154 with ischemic stroke and 35 with ICH), it was found that ischemic stroke patients had a higher RBP-4." (PMID 37892701, 2023). "In addition, some studies have proved that serum markers had a certain advantage in distinguishing hemorrhagic stroke and ischemic stroke, including glial fibrillary acidic protein (GFAP), N-terminal proB-type natriuretic peptide (NT-proBNP), and retinol-binding protein 4 (RBP-4)." (PMID 36864378, 2023).
renal failure (6 papers, 2010 to 2023). "Additionally, some studies have shown a correlation between serum RBP4 levels and renal insufficiency and that NAFLD is associated with reduced glomerular filtration rate and/or microalbuminuria." (PMID 36670387, 2023). "This may in part be caused by the fact that patients with renal insufficiency were excluded from our study to eliminate any effect of abnormal renal function on RBP4 metabolism." (PMID 30135138, 2018).
sarcopenia (6 papers, 2023 to 2026). Progressive decline in muscle mass due to aging which results in decreased functional capacity of muscles. "Higher levels of RBP4 are reportedly associated with an increased risk of sarcopenia, and RBP4 negatively correlates with sarcopenic measurements among Chinese older adults, suggesting its role as a potential biomarker of sarcopenia." (PMID 40641114, 2025). "In their experimental study, RBP4 inhibition exerted a protective effect against fat infiltration and muscle atrophy, implying RBP4 suppression's therapeutic potential in sarcopenia." (PMID 40641114, 2025). "We previous showed that serum RBP4 was elevated in patients with sarcopenia and correlated with the decline of muscle mass and physical dysfunction." (PMID 39031684, 2024). "We previously showed that serum RBP4 was increased and correlated with the severity of sarcopenia in the old adults." (PMID 39031684, 2024). "Moreover, the expression of RBP4 was also detected in skeletal muscle, suggesting a potential RBP4‐mediated cross‐talk between adipose tissue and skeletal muscle in the pathogenesis of sarcopenia." (PMID 39031684, 2024). "Therefore, our results suggest that lowering RBP4 might serve as a promising therapeutic approach for the prevention and treatment of muscle atrophy (sarcopenia)." (PMID 39031684, 2024). "Retinol binding protein 4 (RBP4) is an adipokine that has been demonstrated to be correlated with the presence and severity of sarcopenia in the elderly." (PMID 39031684, 2024). "A clinical study has shown that circulating RBP4 levels are closely related to SMM and muscle function among elderly individuals, making it a useful biomarker for screening sarcopenia." (PMID 37525169, 2023). "From a clinical perspective, genes such as RBP4 and FNDC5 could serve as promising biomarkers for the early detection and monitoring of metabolic–muscular dysfunction in both sarcopenia and T2DM." (PMID 40869253, 2025). "Middle-aged and elderly individuals with lower skeletal muscle function and BMD had higher expression levels of LEP, ADIPOQ, RBP4, DPP4 and inflammatory markers, suggesting that adipokines may play a role in the activation of inflammation and lead to the development of sarcopenia and osteoporosis." (PMID 37525169, 2023).
Stargardt disease (6 papers, 2021 to 2026). "There are preliminary data on a phase 1b/2 clinical trial of Tinlarebant—an oral RBP4 antagonist, showing its potential in slowing or preventing new lesions in Stargardt disease." (PMID 38792644, 2024). "Examples include oral LBS-008 (Tinlarebant), a small molecule retinol binding protein 4 (RBP4) antagonist that is being evaluated in Stargardt Disease." (PMID 36831096, 2023). "RBP4 has mostly been linked in ophthalmology with the atrophic form of AMD and Stargardt disease." (PMID 38792644, 2024). "RBP4-inhibitors could be helpful if proven beneficial in ABCA4 Stargardt disease (NCT05244304)." (PMID 37331655, 2023). "In mouse models of Stargardt disease, dietary modulation of RBPR2 mRNA expression and serum RBP4-ROL levels protects against lipofuscin accumulation and attenuates retinal cell degeneration, suggesting translational relevance." (PMID 41829974, 2026). "Tinlarebant, an oral retinol-binding protein 4 (RBP4) inhibitor currently undergoing phase III testing in the DRAGON trial, has received FDA Breakthrough Therapy designation for Stargardt disease (STGD1) due to its ability to limit retinoid flux to the retina." (PMID 41516080, 2025). "Retinol-binding protein 4 (RBP-4) not only has GO term annotations for its involvement in visual perception and the metabolism of retinol, but it has been described as a potential target in treating atrophic AMD and Stargardt's disease." (PMID 35155457, 2021).
amyloidosis (5 papers, 2018 to 2025). A disorder characterized by the localized or diffuse accumulation of amyloid protein in various anatomic sites. "While the cross interaction of compounds with RBP4 may have the capacity to reduce amyloidosis by restricting RBP4 to interact with Transthyretin." (PMID 39446901, 2024).
cardiac hypertrophy (5 papers, 2018 to 2024). "B(a) P was reported to cause defect of cardiovascular development by aryl hydrocarbon receptor or up regulated of rbp4 and may results in cardiac hypertrophy by activating TLR4/MyD88 signal pathway." (PMID 30112104, 2018). "Overall, these findings suggest that RBP4, through the TLR4-mediated signaling pathway, not only directly impair GLUT4 expression in cardiomyocytes but also promote expression of pro-inflammatory cytokines and cardiac hypertrophy." (PMID 33324685, 2020).
cerebral infarction (5 papers, 2012 to 2023). An ischemic condition of the brain, producing a persistent focal neurological deficit in the area of distribution of the cerebral arteries. "RBP4 is a novel adipokine; however, the exact mechanism of its involvement in cerebral infarction is not fully understood." (PMID 36304097, 2022). "This study aimed to investigate the changes in serum RBP4 levels in elderly patients with cerebral infarction and their relationship with oxidative stress and carotid atherosclerotic plaques so as to provide a reference for clinical diagnosis and treatment." (PMID 36304097, 2022). "More in-depth molecular biological studies should be performed to elucidate the exact mechanism of RBP4 involvement in the development of cerebral infarction in elderly patients." (PMID 36304097, 2022). "It suggested that the elevated level of RBP4 in elderly patients with cerebral infarction promoted oxidative stress injury, which might be one of the important mechanisms of occurrence and development of cerebral infarction." (PMID 36304097, 2022). "Serum levels of RBP4 and 8-iso-PGF2α were significantly higher, whereas serum level of CAT was significantly lower in patients with cerebral infarction compared with controls (P < 0.01)." (PMID 36304097, 2022). "This study found that the serum level of RBP4 not only positively correlated with carotid artery IMT and atherosclerotic plaque area but also significantly positively correlated with the serum level of 8-iso-PGF2α and negatively correlated with CAT level in elderly patients with cerebral infarction." (PMID 36304097, 2022).
dyslipidaemia (5 papers, 2014 to 2025). "Previous studies indicate that RBP4 levels are associated with dyslipidaemia and increased cholesterol levels." (PMID 41144502, 2025).